CRP (C-reactive protein)
Diseases named in the same sentence as CRP in open-access papers (continued):
Sharing a sentence is not in itself a finding about the gene and the disease.
psoriatic arthritis (77 papers, 2009 to 2026). Joint inflammation associated with psoriasis. "Two intervention studies in psoriatic arthritis found that weight loss improves C-reactive protein concentrations, quality of life and disease activity, although these studies were limited by relatively small sample sizes of 46 and 126 participants." (PMID 39282621, 2024). "The analysis revealed that the association between PLR and CRP with the diagnosis of psoriatic arthritis remained statistically significant in the multivariate analysis (PLR: OR = 7.027, p = 0.040; CRP: OR = 3.179 p = 0.022)." (PMID 37109382, 2023). "The results showed that MLR (OR = 2.355, p = 0.039), PLR (OR = 5.775, p = 0.005), SIRI (OR = 2.423, p = 0.044) and CRP (OR = 3.251, p = 0.008) were associated with a higher probability of diagnosis with psoriatic arthritis by univariate analysis." (PMID 37109382, 2023). "In this case report, we describe a patient with chronic psoriatic arthritis that cause impairing pain, increased C-reactive protein levels (CRP) and depressive symptoms." (PMID 20157432, 2010). "In addition, as the serum level of S-calprotectin in patients with psoriatic arthritis increased, S100A8/9, which is associated with psoriatic arthritis pathogenesis, became a better predictor of ongoing disease than CRP or other pro-inflammatory cytokines." (PMID 29942307, 2018). "Components of the clinical disease activity index for psoriatic arthritis and C-reactive protein level by type of pain." (PMID 38327709, 2024). "Patients presenting with higher platelet/lymphocyte ratio (PLR) or CRP values were more likely to be diagnosed with psoriatic arthritis than with psoriasis vulgaris in the multivariate regression analysis." (PMID 37109382, 2023). "Inflammatory markers such as erythrocyte sedimentation rate and C-reactive protein may be elevated in cases with active psoriatic arthritis." (PMID 41393637, 2025). "Thus, patients with higher PLR or CRP values at the time of initial presentation were more likely to be diagnosed with psoriatic arthritis than with psoriasis vulgaris." (PMID 37109382, 2023). "However, the effect estimate of CRP on DBP, serum albumin, and psoriatic arthritis showed nominal association at p < 0.05." (PMID 27327646, 2016). "CRP is a well-established biomarker of systemic inflammation and synovitis, and it is routinely incorporated into composite disease activity indices for PsA, such as the Disease Activity Index for Psoriatic Arthritis (DAPSA) and the Psoriatic Arthritis Disease Activity Score (PASDAS)." (PMID 40572738, 2025). "This table summarizes the disease characteristics, skin lesion topography, inflammatory markers (CRP levels), and disease activity (DASPA scores) for patients with psoriatic arthritis." (PMID 41211170, 2025). "The Disease Activity Index for Psoriatic Arthritis (DAPSA), which includes joint counts, pain scores, patient global assessment, and C-reactive protein levels, is increasingly used in newer trials." (PMID 41189198, 2025). "The modified Disease Activity Index of Psoriatic Arthritis (DAPSA28) was calculated, and RDW, MPV, NLR, CRP, and ESR were measured." (PMID 38584198, 2024). "A Cox regression proportional hazard analysis was performed to compare the diagnosis of psoriatic arthritis versus psoriasis vulgaris based on NLR, MLR, PLR, SIRI, SII, and CRP values." (PMID 37109382, 2023). "AS: ankylosing spondylitis; PsA: psoriatic arthritis; EnA: enteropathic arthritis; SD: standard deviation; CRP: C-reactive protein; ASDAS: ankylosing spondylitis disease activity score; BASDAI: bath ankylosing spondylitis disease activity index." (PMID 33447495, 2021).
psoriatic arthritis (continued). "This contrasts with findings in other inflammatory diseases, such as rheumatoid and psoriatic arthritis, where t-VNS resulted in decreased levels of CRP." (PMID 34832948, 2021). "In contrast, MTX, an anti-inflammatory drug that is widely used to treat patients with RA and psoriatic arthritis, did not reduce inflammatory markers, such as interleukin-1, interleukin-6, C-reactive protein, or cardiovascular events in the CIRT trail." (PMID 33416495, 2021).
diabetic nephropathy (76 papers, 2009 to 2026). "A recent study showed that hs‐CRP levels were positively associated with the development of diabetic nephropathy." (PMID 37102663, 2023). "Multivariable logistic regression analyses showed that frequency of diabetes kidney disease, ionized calcium and C-reactive protein were independently associated with leukocyte count positively." (PMID 33633262, 2021). "CRP is a marker of inflammation and has been reported to be associated with the development of diabetic nephropathy." (PMID 30841605, 2019). "CRP, a biomarker of inflammation, has been widely reported to be associated with the development of diabetic nephropathy." (PMID 30841605, 2019). "Observational studies have shown positive associations between inflammatory mediators, such as C-reactive protein, and the development of diabetic kidney disease." (PMID 29910771, 2018). "The results of present study show that IL-19 levels was significantly elevated in the patients with diabetic nephropathy and was associated with Hs-CRP, Cystatin C, UAE and HbA1c." (PMID 28201997, 2017). "The multifactorial model, which includes RSFd, RSFI, age, and CRP, performed well and may provide potential imaging indicators for the identification and risk assessment of early diabetic nephropathy." (PMID 41556048, 2026). "Furthermore, statins were associated with substantially reduced risk of CV death, all-cause death and 3P-MACE after adjusting for gender, age, diabetic nephropathy, BMI, receiving beta blockers, hs-CRP, and LDL-C level." (PMID 35054080, 2022). "The Finnish Diabetic Nephropathy Study demonstrated that hs-CRP levels are only borderline associated with the progression to a composite kidney outcome (higher albuminuria concentration or ESKD) in 1564 patients with type 1 diabetes after 5.8 years of follow-up." (PMID 32587865, 2020). "In addition, DR is also associated with markers of diabetic kidney disease, including microalbuminuria and serum creatinine, and cardiovascular disease markers, such as raised C-reactive protein (CRP)." (PMID 33198349, 2020). "From an epidemiological perspective, flavanols, flavones, and anthocyanidins could decrease the risk of diabetic nephropathy, and the consumption of a diet rich in flavonoids could reduce the risk of diabetic retinopathy and decrease the levels of HgbA1C and C-reactive protein." (PMID 39064844, 2024). "A similar analysis described higher risks of microvascular complications, particularly diabetic kidney disease, again mediated by BMI and CRP." (PMID 41010537, 2025). "Beyond enhancing NLRP3 expression through FcγRs/NF-κB signaling, CRP promotes diabetic nephropathy progression through Smad3-mediated activation of NLRP3 inflammasomes." (PMID 41377556, 2025). "Vandana Varma also reported elevated serum C‐reactive protein (CRP) levels in patients with diabetic nephropathy." (PMID 40804707, 2025). "Meanwhile, inflammatory markers such as CRP and leukocyte count also retained predictive value, supporting the role of systemic inflammation in diabetic kidney disease pathogenesis." (PMID 41303131, 2025). "Higher CRP concentrations were also found in the diabetic nephropathy group with the G/G genotype (p < 0.001) and in the kidney transplant diabetic nephropathy group with the G/G genotype (p < 0.001) compared to the control group with the same genotype." (PMID 39061907, 2024). "In the context of diabetic nephropathy, CRP exacerbates its development by inhibiting autophagy in podocytes through the suppression of signaling in the C3a/C3aR axis." (PMID 38281018, 2024). "High levels of CRP are linked to a higher risk of CVD and mortality in T2DM, and there is correlation between hs-CRP and diabetic kidney disease." (PMID 38140319, 2023). "Elderly, male, primary disease was hypertensive renal damage or diabetic nephropathy, hypoproteinemia and high CRP level, all of which will lead to increased mortality in MHD patients." (PMID 37682194, 2023).
diabetic nephropathy (continued). "Inflammatory markers, such as C-reactive protein (CRP), have been associated with diabetic nephropathy and proteinuria." (PMID 37791152, 2023). "Although there is a large body of evidence suggesting connections between inflammation and diabetic nephropathy, the findings regarding relationships between CRP and diabetic nephropathy are inconsistent throughout the literature." (PMID 37916147, 2023). "A previous study showed that tubular CRP staining was increased with declining renal function and increasing severity of histological lesions in patients with advanced diabetic nephropathy." (PMID 37545739, 2023). "The novel inflammatory predictor, such as C-reactive protein to serum albumin ratio, is higher in diabetic nephropathy." (PMID 37612612, 2023). "Elderly, male, primary disease was hypertensive renal damage or diabetic nephropathy, hypoproteinemia and high C-reactive protein level, all of which will lead to increased mortality in MHD patients." (PMID 37682194, 2023). "In response to the onset of inflammation (such as diabetic nephropathy, thyroiditis, and hepatitis), CRP binds to pathogens and promotes their elimination by phagocytic cells, serving as the first line of innate host defense." (PMID 37484181, 2023). "A study of CRP-driven diabetic nephropathy showed that CRP triggers the aggregation of DPP4 and CD32b at the protein level to form DPP4/CD32b/NF-κB signaling." (PMID 37893085, 2023). "Six significant mediators were detected on the associations of lifestyle score with risk of the composite microvascular complications and diabetic kidney disease, namely, albumin, HDL-C, triglycerides, apolipoprotein A, CRP, and HbA1c." (PMID 36626356, 2023). "The covariates for assessing infection-related mortality included age, sex, the presence of diabetic nephropathy, dialysis history, nPCR, Kt/V for urea, body mass index, and serum concentrations of albumin, urea nitrogen, and C-reactive protein." (PMID 31988325, 2020). "Effector molecules of the innate immune system including C-reactive protein, interleukin-6, and tumor necrosis factor-α are increased in patients with diabetic kidney disease." (PMID 29910771, 2018). "There were significant differences in sex, presence of diabetic nephropathy, HD vintage, serum albumin, serum phosphate, C-reactive protein, intact parathyroid hormone, Kt/V, and GNRI." (PMID 29558928, 2018). "To date, the most consistent animal data in CRP research were obtained with the diabetic mouse model of CRP; CRP was shown to clearly enhance renal fibrosis in diabetic nephropathy (T2DN) via CD32b-Smad3-mTOR signaling." (PMID 29951057, 2018). "The diabetic nephropathy group had significantly higher triglyceride, N-terminal pro-brain natriuretic peptide (NT-proBNP), and C-reactive protein (CRP) levels and significantly lower high-density lipoprotein (HDL)-cholesterol levels." (PMID 26839894, 2016). "Increases in serum cTnT were associated with higher cTnT concentrations in the present cross-sectional study (age, eQB, serum phosphorus, serum CRP, diabetic nephropathy, and serum albumin), consistent with previous studies." (PMID 26603871, 2016). "Also, higher CRP concentrations were found in the kidney transplant diabetic nephropathy group with the T/T genotype compared to the control group with the same genotype (p = 0.001)." (PMID 39061907, 2024). "Higher CRP concentrations were also observed in the diabetic nephropathy group with the 4b/4b genotype (p = 0.028) and in the kidney transplant diabetic nephropathy group with the 4a/4b genotype (p = 0.002) and the 4b/4b genotype (p = 0.014) compared to the control groups with the same genotypes." (PMID 39061907, 2024). "Additionally, in the same study, the serum CRP was significantly higher among those experiencing diabetic nephropathy." (PMID 35300754, 2022). "Also, a study reported that circulating CRP was positively correlated with hepcidin in CHD patients with diabetic nephropathy." (PMID 29312624, 2017).
diabetic nephropathy (continued). "Patients in higher quartiles were more likely to have ischaemic/hypertensive nephropathy or diabetic kidney disease as their primary renal disease and less likely to have glomerulonephritis, and also had worse renal function (lower eGFR and higher cystatin C), higher CRP, and higher serum cFLC." (PMID 28403201, 2017). "Furthermore, blockade of mTOR signaling with rapamycin was also able to inhibit CRP and /or high glucose-induced upregulation of collagen I and CTGF expression, demonstrating mTOR signaling as a central mechanism by which CRP promotes diabetic kidney disease in T2DN." (PMID 27221338, 2016). "A lack of association between IL6 G-174C or IL1 RA genotypes and significant association between CRP and diabetic nephropathy has been reported earlier too, indicating that elevated CRP levels are associated with diabetic nephropathy independent of polymorphisms in cytokine genes." (PMID 19357773, 2009). "In this research, we investigated the role of vitamin D and basic inflammatory biomarkers, serum highly sensitive CRP (hs‐CRP) and TNF‐α, and their possible interactions in diabetic kidney disease in an Iranian population." (PMID 40804707, 2025). "In terms of inflammation markers, CRP levels were significantly higher in both the T2DM and diabetic nephropathy groups." (PMID 40731875, 2025). "Moreover, another meta-analysis of 3,426 patients with early diabetic nephropathy concluded that statins could increase eGFR, reduce serum creatinine (Scr), and decrease C-reactive protein (CRP) level, thus reducing the inflammatory response and protecting the kidney." (PMID 40171201, 2025). "The CRP level of the control group was lower than that of the patients with T2DM and diabetic nephropathy (p = 0.002)." (PMID 40731875, 2025). "Studies have shown reductions in C-reactive protein (CRP) and oxidative stress, suggesting protective effects in diabetic nephropathy and cardiovascular disease." (PMID 41356003, 2025). "It has been reported that SGLT2 inhibition attenuates inflammation, including levels of CRP, IL-6, and TNF-α, and the progression of diabetic nephropathy." (PMID 35676606, 2022). "We reported CRP can activate NF-κB-mediated renal inflammation and TGF-β/Smad3-mediated renal fibrosis via CD32b in diabetic kidney disease." (PMID 34671208, 2021). "C reactive protein (CRP) and mean corpuscular volume-to-lymphocyte ratio (MCVL) were higher in patients ongoing hemodialysis; systemic immune-inflammation index (SII) was higher in diabetic nephropathy." (PMID 41226704, 2025). "Serum bilirubin levels are positively correlated with the levels of the antioxidative enzymes as superoxide dismutase, catalase, and glutathione peroxidase, while it is inversely correlated with C-reactive protein, TNF-α, interleukin (IL)-2, IL-6, and IL-10 release in diabetic kidney disease." (PMID 35327498, 2022). "Third, data on some important variables that can influence diabetic nephropathy, such as smoking history, albumin, C-Reactive protein, and CKD etiology, were lacking." (PMID 34461808, 2021). "Furthermore, compared with nephrosclerosis, diabetic nephropathy was characterized at RRT initiation by higher BMI, higher systolic and diastolic BPs, and higher CRP, NT-proBNP, and albuminuria levels as well as lower age and serum albumin levels." (PMID 26839894, 2016). "On the other hand, the median weight, waist circumference, BMI, blood Hb and Htc, blood platelet count, serum albumin, C-reactive protein, HbA1c, fasting glucose, eGFR, and serum lipids of the patients, with and without diabetic nephropathy, were significantly different (p < 0.05 for all)." (PMID 37762893, 2023). "Moreover, vitamin D is essential for protecting kidney function through reducing 24 h urine protein and inflammatory status (CRP, TNF- α, IL-6) in patients with diabetic nephropathy, but without effects on eGFR." (PMID 36900141, 2023).